IDH3B (isocitrate dehydrogenase (NAD(+)) 3 non-catalytic subunit beta)
Description:
Plays a structural role to facilitate the assembly and ensure the full activity of the enzyme catalyzing the decarboxylation of isocitrate (ICT) into alpha-ketoglutarate. The heterodimer composed of the alpha (IDH3A) and beta (IDH3B) subunits and the heterodimer composed of the alpha (IDH3A) and gamma (IDH3G) subunits, have considerable basal activity but the full activity of the heterotetramer (containing two subunits of IDH3A, one of IDH3B and one of IDH3G) requires the assembly and cooperative function of both heterodimers.
Synonyms: RP46
Tractability: Small molecule: a structure with a bound ligand is known. PROTAC: ubiquitination databases record sites on it; its protein half-life has been measured.
Gene: Protein-coding gene on chromosome 20 (2,658,393 to 2,664,219, reverse strand). Ensembl gene ENSG00000101365.
Subcellular location: Mitochondrion
Subcellular location (Human Protein Atlas): Mitochondria
Pathways (Reactome):
Metabolism: Citric acid cycle (TCA cycle)
Gene Ontology:
Molecular function: electron transfer activity; isocitrate dehydrogenase (NAD+) activity; magnesium ion binding; NAD binding; oxidoreductase activity, acting on the CH-OH group of donors, NAD or NADP as acceptor
Biological process: tricarboxylic acid cycle; isocitrate metabolic process
Cellular component: isocitrate dehydrogenase complex (NAD+); mitochondrion; nucleus; mitochondrial matrix
Genetic constraint (gnomAD): Loss-of-function variants: 40 observed, 50.22 expected, observed/expected ratio (o/e) 0.8, 90% interval 0.62 to 1.04. The upper end of that interval is the gene's LOEUF score, 1.04, which puts it in group 4 of 6, group 1 being the genes least tolerant of losing a copy. Missense variants: 450 observed, 536.22 expected, observed/expected ratio (o/e) 0.84, 90% interval 0.78 to 0.91. Synonymous variants: 185 observed, 203.37 expected, observed/expected ratio (o/e) 0.91, 90% interval 0.81 to 1.03.
Homologues: Orthologues: dog IDH3B (96% identical), rabbit IDH3B (95% identical), guinea pig IDH3B (95% identical), macaque IDH3B (94% identical), mouse Idh3b (94% identical), rat Idh3b (93% identical), pig IDH3B (91% identical), chimpanzee IDH3B (90% identical), tropical clawed frog idh3b (80% identical), zebrafish idh3b (77% identical), Caenorhabditis elegans idhb-1 (57% identical), Drosophila melanogaster Idh3b (56% identical). Paralogues in human: IDH3G (49% identical), IDH3A (40% identical).
Diseases named in the same sentence as IDH3B in open-access papers:
IDH3B is named in the same sentence as 24 diseases in open-access papers, as found by Europe PMC text mining. Sharing a sentence is not in itself a finding about the gene and the disease. The quoted sentences say what the papers report.
retinal degeneration (4 papers, 2018 to 2022). Degeneration of the retina. "Patients with IDH3A mutations showed an early onset (1–11 years old) of retinal degeneration, and patients with IDH3B mutation showed a late onset (30–50 years old) of retinal degeneration." (PMID 35985423, 2022). "Mutations of IDH3A and IDH3B are identified in patients with inherited retinal degeneration, pseudocoloboma, and epileptic encephalopathy." (PMID 35985423, 2022). "It was shown that human IDH3A and IDH3B mutations are associated with severe early childhood-onset retinitis pigmentosa, and mouse Idh3a mutations lead to retinal degeneration." (PMID 35360866, 2022). "Biallelic recessive variants in the a and b genes, IDH3A and IDH3B, induce retinal degeneration and encephalopathy." (PMID 33426505, 2020). "Two families with homozygous mutations in IDH3B, and which exhibited non-syndromic retinal degeneration, have also been described." (PMID 30478029, 2018). "Loss-of-function and missense mutations in both IDH3A and IDH3B have previously been implicated in families exhibiting retinal degeneration." (PMID 30478029, 2018). "We considered the missense mutation, E229K, in Idh3a to be the likely causative mutation, as human patients with mutations in either IDH3A or IDH3B exhibit retinal degeneration." (PMID 30478029, 2018). "As human patients with apparent loss-of-function mutations in IDH3B seem only to have retinal degeneration, we produced a CRISPR/Cas9-induced mutation in the mouse Idh3b gene." (PMID 30478029, 2018). "Loss-of-function Idh3b mutants do not exhibit the same retinal degeneration phenotype, with no signs of retinal stress or reduction in mitochondrial respiration." (PMID 30478029, 2018). "It is possible that human IDH3B mutants may have an unknown malfunction such as gain of function and nonmetabolic function to cause retinal degeneration, which has been identified in mutations of other enzymes." (PMID 35985423, 2022). "Global deletion of Idh3b only causes male infertility but not retinal degeneration in mice." (PMID 35985423, 2022). "The human patients with clear null mutations in IDH3B develop RP in adulthood; the mutant mice might not live long enough to develop retinal degeneration, or this might simply reflect species differences." (PMID 30478029, 2018). "Dysfunction of IDH3B, the β subunit of IDH3, has been previously correlated with retinal degeneration and male infertility in humans, but tissue-specific effects of IDH3 dysfunction are unclear." (PMID 35985423, 2022). "Together, these results demonstrate that Idh3b-KO mice have normal vision and retinal morphology without retinal degeneration." (PMID 35985423, 2022). "In contrast to Idh3a mutants, Idh3b mutant mice are fully viable and show no signs of retinal degeneration within 6 months of age." (PMID 30478029, 2018). "Modelling human patient mutations in which Idh3b, the regulatory subunit of IDH3, is absent does not result in retinal degeneration in mice within 6 months of age, reflecting the later onset of RP in the patients." (PMID 30478029, 2018).
retinitis pigmentosa (3 papers, 2009 to 2022). Retinitis pigmentosa (RP) is an inherited retinal dystrophy leading to progressive loss of the photoreceptors and retinal pigment epithelium and resulting in blindness usually after several decades. "Homozygous loss-of-function mutation of Idh3b is associated with mitochondrial dysfunction in retinitis pigmentosa." (PMID 34200203, 2021). "Recently, a loss-of-function of IDH3B, the β-subunit of NADH-IDH, was found in patients with retinitis pigmentosa." (PMID 19476632, 2009).
Encephalopathy (2 papers, 2020 to 2025). Encephalopathy is a term that means brain disease, damage, or malfunction. "Interestingly, changes in FGF21-responsive genes such as OXCT1, the SUCL complex, PDHA1, OGDH, ACO2, IDH3B, and ETC components (MT-CO2, COQ9, UQCRQ, SDHB/D and NDUFB7) are linked to mitochondrial deficiency syndromes manifesting cardiomyopathy and encephalopathy." (PMID 40998786, 2025).
atrial fibrillation (1 paper, 2021). A disorder characterized by an electrocardiographic finding of a supraventricular arrhythmia characterized by the replacement of consistent P waves by rapid oscillations or fibrillatory waves that vary in size, shape and timing and are accompanied by an irregular ventricular response. "Therefore, future studies are needed to investigate the role of the RyR2/Idh3b interaction in cardiac physiology and pathophysiology, especially with respect to atrial fibrillation." (PMID 34200203, 2021). "Interestingly, Idh3b was found to be downregulated at the mRNA level in a canine model of atrial fibrillation and also dysregulated in left atrial tissue from patients with atrial fibrillation." (PMID 34200203, 2021).
autosomal recessive retinitis pigmentosa (1 paper, 2009). Autosomal recessive retinitis pigmentosa (RP) is an autosomally recessive inherited retinal dystrophy leading to progressive loss of the photoreceptors and retinal pigment epithelium and resulting in blindness usually after several decades. "Mutations in IDH3B, an enzyme participating in the Krebs cycle, have recently been found to cause autosomal recessive retinitis pigmentosa (arRP)." (PMID 20011630, 2009).
breast carcinoma (1 paper, 2020). "IDH3B is upregulated in breast cancer and is significantly involved in energy metabolism in tumor progression." (PMID 32293263, 2020).
cardiac hypertrophy (1 paper, 2020). "Fatty acid oxidation (Acadm, Etfdh, Acadl, Acadvl, Eci1, Hadh, Phyh, Acaa2, Hadha, Hadhb, Cd36), glucose metabolism (Dld, Pdha1, Pgam1, Pgam2, Acss1, Ldhb, Fh1, Slc2a4, Aldh6a1), TCA cycle (Aco2, Dld, Fh1, Ogdh, Sucla2, Sdha, Idh3b, Idh2) were up-regulated by hispidulin in cardiac hypertrophy." (PMID 33324687, 2020).
cataract (1 paper, 2020). Partial or complete opacity of the crystalline lens of one or both eyes that decreases visual acuity and eventually results in blindness. "As reported in a previous IDH3B‐linked RP case, early onset subcapsular cataracts developed in our patient, suggesting an incipient genotype–phenotype correlation for IDH3B‐related RD." (PMID 31736247, 2020).
Cognitive impairment (1 paper, 2022). Abnormal cognition is characterized by deficits in thinking, reasoning, or remembering. "We also found that 117 DEPs, including ADAM10, were closely associated to the AD‐specific β‐amyloid and tau pathologies; and the changes of IDH3B and RTN1 had a potential diagnostic value for cognitive impairment analyzed by machine learning." (PMID 36254251, 2022).
glioma (1 paper, 2025). A benign or malignant brain and spinal cord tumor that arises from glial cells (astrocytes, oligodendrocytes, ependymal cells). "Immune-related pathways such as TNF signalling (IDH3B/G, MDH1, ACO2, SDHA, OGDHL) and JAK/STAT3 (PIAS2/3, PTPN2, AKT1/2, MCL1, CISH, AOX1) signalling are enriched in gliomas and play a critical role in their progression." (PMID 41007296, 2025).
glucose metabolism disorders (1 paper, 2022). "The expression changes of IDH3B may be an alternative way to detect brain glucose metabolism disorders in AD patients." (PMID 36254251, 2022).
infertile (1 paper, 2022). "IDH3B proteins are underexpressed in low motile spermatozoa or spermatozoa from infertile men with varicocele." (PMID 35985423, 2022).
major depressive disorder (1 paper, 2016). An episode of depression lasting two or more weeks without an intervening episode of mania. "We examined whether protein expression of IDH3A and IDH3B in the cerebellum and parietal cortex (BA7) differed between samples from patients with BD, major depressive disorder or schizophrenia, and controls." (PMID 26782057, 2016).
male infertility (1 paper, 2022). The inability of the male to effect fertilization of an ovum after a specified period of unprotected intercourse. "The disruption of key enzymes in PUFA synthesis such as acyl-CoA synthetase 6 and delta-6 desaturase can arrest spermiogenesis, resulting in male infertility with similar phenotypes to the Idh3b-KO mice." (PMID 35985423, 2022). "Significantly, reduced IDH3B is found in spermatozoa from patients with male infertility and poor sperm motility." (PMID 35985423, 2022).
mesothelioma (1 paper, 2023). A usually malignant and aggressive neoplasm of the mesothelium which is often associated with exposure to asbestos. "Other highly expressed genes in sarcomatoid mesothelioma cell lines were two ATP synthase subunits (ATP5H, ATPO), MTCO2, COX5B, COX 6C2, IDH3A, IDH3B and TIMM9." (PMID 37297007, 2023).
ovarian carcinoma (1 paper, 2022). A malignant neoplasm originating from the surface ovarian epithelium. "In parallel, TRPM7 silencing decreased the glucose uptake of tumor-bearing mice and TRPM7 levels were negatively correlated with IDH3B and UQCRC1, but positively with HK2 and PDK1 expression in ovarian cancer tissues." (PMID 35101076, 2022). "The impacts of TRPM7 silencing on the levels of glycolysis-related HK2, PDK1 and oxidative phosphorylation (OXPHOS)-related IDH3B and UQCRC1, HIF-1α expression and AMPK phosphorylation were determined in ovarian cancer." (PMID 35101076, 2022). "To understand how TRPM7 modulated metabolic reprogramming in ovarian cancer, we analyzed the expression of TRPM7, glycolysis-related HK2, PDK1, and OXPHOS-related IDH3B and UQCRC1 in 60 ovarian cancer tissues by IHC." (PMID 35101076, 2022). "Furthermore, TRPM7 silencing also decreased the relative levels of glycolysis-related HK2 and PDK1 expression as well as PKM2 nuclear translocation, but increased OXPHOS-related IDH3B and UQCRC1 expression in ovarian cancer cells and tissues." (PMID 35101076, 2022).
tumor (10 papers, 2011 to 2025). "However, IDH3B has been suggested to be a hub gene that drives tumour associated cellular pathways, and it could be functioning in a similar manner when its expression is potentially driven by E1A 13S." (PMID 32503156, 2020). "Here, we show for both the IDH2 and IDH3A/IDH3B genes expression is mainly correlated in tumor samples exhibiting deleted copy number to normal copy number." (PMID 22174824, 2011). "A number of mitochondrial proteins with relevance to tumour pathophysiology were altered, including BSG, SNCB and three Isocitrate dehydrogenase 3 forms (IDH3A, IDH3B, and IDH3G)." (PMID 24728830, 2014). "Immunohistochemical analysis of tumor tissues revealed that Liensinine treatment led to a marked reduction in the expression levels of HK2, PDK1, and HIF-1α, while increasing the expression of IDH3B, UQCRC1, and phosphorylated AMPK (P-AMPK)." (PMID 40665352, 2025). "Several proteins, for example BSG (increased in GBM), SNCB (decreased in GBM) and IDH3 (with IDH3A, IDH3G and IDH3B all decreased in GBM), did not fall into an obvious functional grouping but are pertinent to tumour pathophysiology (see “Discussion” section)." (PMID 24728830, 2014).
cancer (2 papers, 2021 to 2023). A tumor composed of atypical neoplastic, often pleomorphic cells that invade other tissues. "To further explore the role of the gene set (DLAT, IDH3B, and MAP3K4) across diverse cancer types, we analyzed their expression levels and mutant profiles." (PMID 36835825, 2023). "AURKA and IDH3B are not present in any of the lists of cancer genes, whereas CDK8, MARCH7, YAP1, and YES1 are found among the more than 9000 candidate cancer genes identified by forward genetic screens in mice." (PMID 33427197, 2021).
IDH3B also shares sentences with these, for which no sentence is quoted: autosomal dominant retinitis pigmentosa (1 paper); cardiomyopathy (1); cognitive decline (1); glioblastoma (1); schizophrenia (1); varicocele (1).